TNFAIP3 (TNF alpha induced protein 3)
Diseases named in the same sentence as TNFAIP3 in open-access papers (continued):
Sharing a sentence is not in itself a finding about the gene and the disease.
tumor (97 papers, 2008 to 2026). "Remarkably, TNFAIP3 manifested the most frequent truncating mutations and deletions consistent with the loss-of-function of tumor suppressor, with 7 frameshift deletions, 1 frameshift insertion, and 1 nonsense mutation." (PMID 35359413, 2022). "Tumor occurrence and development is a complex biological process, with a variety of associated genes like zinc finger protein (TNFAIP3) and nuclear factor κB protein, which play an essential role in tumor occurrence and development." (PMID 36033828, 2022). "Another gene recurrently mutated in LGLL is TNFα-induced protein 3 (TNFAIP3), a tumor suppressor encoding A20, a negative regulator of nuclear factor kappa B (NFkB)." (PMID 34660312, 2021). "The genes SMAD7, TGFBR2 and TNFAIP3 were associated with both tumour suppressor and oncogenic roles." (PMID 34198662, 2021). "The genetic inactivation or mutation of TNFAIP3 led to constitute activation of NF-κB to enable tumor cell survival." (PMID 32968045, 2020). "Key signaling molecules exclusively affected by tumor-priming include MAP2K3, MARCKSL1, STAT5A, and TNFAIP3, which are specifically associated with NK cell cytotoxicity against tumor targets." (PMID 31242243, 2019). "TNFAIP3 encodes a zinc finger protein that serves as a tumor suppressor through its potent inhibition of the NF-κB signaling pathway." (PMID 29383146, 2017). "Next, we evaluated whether p65 and p50 nuclear translocation in doxorubicin-treated tumor specimens was associated with an increase in the expression of NF-κB target genes TNFAIP3, ICAM-1 and CXCL-1." (PMID 24344116, 2014). "In cancer biology, TNFAIP3 has been reported to play context‐dependent roles—acting as either a tumor suppressor by limiting chronic inflammation or as an oncogene by promoting cancer cell survival." (PMID 41461391, 2026). "The pathogenesis of THRLBCL involves several genetic alterations also seen in DLBCL, including overexpression of BCL2 and mutations in TNFAIP3 and MYD88 (L265P), which promote tumor cell survival." (PMID 41141099, 2025). "P.g. also manipulates inflammatory signaling in SCC-25 cells by activating NF-κB and MAPK pathways, driving tumor-associated inflammation and metastasis via upregulation of CCL20, TNFAIP6, CXCL8, TNFAIP3, TRAF5, CYP1A1, and NOD2 gene expression." (PMID 40924302, 2025). "We found that the expression of TNFAIP3 was significantly higher in tumour tissue compared with adjacent tissue." (PMID 39724264, 2025). "The TNFAIP3 protein was immunofluorescently stained in tumour tissue sections from animal experiments to observe it change after ZSH‐2208 treatment in subcutaneous tumours of nude mice." (PMID 39724264, 2025). "The macrophagehigh ductal cell type 2 samples showed a higher number of tumor cells expressing the NF-κB target genes TNFAIP3 and CXCL1 compared to macrophagelow samples, consistent with the known role of TNF in activating NF-κB signaling in PDAC." (PMID 40634284, 2025). "In contrast, miRNAs that were downregulated in rKGAS cells were shown to regulate tumor suppressor genes including IGF1R, TNFAIP3, and MTOR, suggesting a potential loss of tumor-suppressive signaling in rKGAS cells." (PMID 40952575, 2025). "Subsequently, at the Post‐NT state, these cells displayed increased synthesis of T‐cell suppressive factors such as Tnfaip3, Ccl5 and Ctla4,89, 90, 91 coinciding with tumour emergence." (PMID 40887856, 2025). "Chd2 knockout suppressed both tumor initiation and progression, whereas Tnfaip3 knockout enhanced tumor initiation and overall tumor growth." (PMID 41705258, 2025). "In pancreatic ductal adenocarcinoma (PDAC), TNFAIP3 expression was positively correlated with tumor differentiation, TNM stage, and patient survival, suggesting a potential anti-cancer role." (PMID 40469292, 2025). "Functionally TNFAIP3 is a negative regulator in the NFκB pathway and believed to be a tumor suppressor gene." (PMID 37951851, 2024).
tumor (continued). "We further confirmed our findings on TNFAIP3 implication in SCLC by our analysis on a panel of different tumor types, where TNFAIP3 showed the second lowest expression in SCLC (while the lowest expression was found in NB)." (PMID 36765949, 2023). "Next-generation sequencing revealed six tumor-specific mutated genes (IGH/BCL6, TNFAIP3, PRDM1, CREBBP, DTX1, and FOXO1)." (PMID 37884941, 2023). "The test results showed that the tumor-specific mutations in this sample were as follows: BCL6, TNFAIP3, PRDM1, CREBBP, DTX1, and FOXO1." (PMID 37884941, 2023). "With marked patient occupancy (GBC6), Macro04 exhibited versatile tumor-promoting roles, including cytokine production (e.g., TNFAIP3, CXCL3), pro-angiogenesis (e.g., VEGFA), and ECM remodeling (e.g., SPP1) 28,36,37." (PMID 36198671, 2022). "In previous reports, TNFAIP3 negatively regulates the activity of NF-κB by up-regulating the expression level to inhibit tumor development." (PMID 34526012, 2021). "CA19-9, D-dimer, TNM stage, tumor differentiation grade, and TNFAIP3/A20 were independent prognostic markers for PDAC in univariate and multivariate COX analyses." (PMID 33578593, 2021). "Multivariate Cox analysis identified CA19-9 (P = .005), D-dimer (P = .005), TNFAIP3/A20 (P < .001), TNM stage (P = .007), and tumor differentiation grade (P < .001) as independent risk factors for overall survival." (PMID 33578593, 2021). "TNFAIP3/A20 was found to correlate with tumor differentiation grade (P < .001), BMI (P < .001), TNM stage (P = .014), and survival rate (P < .001)." (PMID 33578593, 2021). "We provide compelling evidence to establish a signaling pathway by which tumor-derived ITGBL1-enriched EVs convert primary fibroblasts to CAFs via binding to TNFAIP3 and activating the NF-κB signaling pathway." (PMID 32139701, 2020). "Consistent results were also observed in the xenograft tumor growth assay in mice, where activation of the iFGFR1 signaling markedly enhanced tumor growth and KO of TNFAIP3 inhibited tumor growth derived from DCIS-iFGFR1 cells." (PMID 30111373, 2018). "In the AP20187-treated TNFAIP3 KO tumors, most tumor areas displayed similar morphologies observed in the vehicle-treated TNFAIP3 KO tumors." (PMID 30111373, 2018). "For cases harboring TNFAIP3 mutations with VAF above 50%, it is likely that in these instances either the second allele is deleted in the tumor cells, or that we observe here uniparental disomy of the mutated allele." (PMID 27566587, 2016). "TNFAIP3, a tumor suppressor and negative regulator of NF-κB, is inactivated by promoter methylation, mutations and/or deletions in about 15-30% of OAML." (PMID 27566587, 2016). "TNFAIP3 inhibits the activity of NF-κB, which strongly facilitates the tumor progression through MMP9 expression, and represses cell division and inflammation." (PMID 26367773, 2015). "Homozygous deletions were found in 11% of our cases, and our findings strongly suggest that TNFAIP3 serves as a tumor-suppressor gene in cHL." (PMID 23039325, 2012). "The heightened inhibition of TNFAIP3 in IDC may contribute to a more aggressive phenotype, whereas the relatively preserved TNFAIP3 levels in ILC could mirror its unique tumor microenvironment." (PMID 41461391, 2026). "In early stages, TNFAIP3 may function as a tumor suppressor by limiting NF‐κB‐mediated chronic inflammation." (PMID 41461391, 2026). "Likewise, adoptively transferred anti-tumor CD8+ T cells harboring a deletion of TNFAIP3 enhanced IFN-γ and TNF-α production and reduced PD-1 expression, which exhibited superior anti-tumor activity in vivo." (PMID 40469292, 2025). "However, both OTUD7B and TNFAIP3 can exert anti-tumor effects by inhibiting the NF-κB signaling pathway in HCC." (PMID 40469292, 2025). "Furthermore, the correlation between patient survival and TNFAIP3 protein expression in tumour tissues was evaluated using survival analysis in R version 4.3.0 software with data from the TCGA database." (PMID 39724264, 2025).
tumor (continued). "Regarding CNV analysis, we found that PANoptosis genes, especially NLRP3, RBCK1, PSTPIP2, and TNFAIP3, may promote tumor progression via CNV alteration." (PMID 36890219, 2023). "TNFAIP3 plays a dual role in cancer: tumor suppressor and oncogene." (PMID 36056685, 2023). "In addition, the knockdown of YTHDF2 and EPHB3 or the knockdown of YTHDF2 and TNFAIP3 promoted the tumor growth in xenograft model under TMZ treatment compared with YTHDF2 silence alone." (PMID 35582627, 2022). "The occurrence and development of CRC are regulated by various genes, and it is speculated that TNFAIP3 is an important factor that promotes tumor development." (PMID 36033828, 2022). "Both the EPHB3 and TNFAIP3 are the typical tumor suppressors." (PMID 35582627, 2022). "Finally, the TNFAIP3 gene is inactivated in ~30% of ABC-DLBCL and particularly in BN2 tumours, which also display mutations in its binding partner TNIP." (PMID 36289712, 2022). "The most frequently mutated genes were STAT, TNFAIP3 and ITPKB, and detection sensitivity was 87.5%, suggesting that ctDNA could well reflect the spectrum of tumor tissue mutation." (PMID 32695399, 2020). "A direct target of miR-125b, the tumor necrosis factor alpha-induced protein 3 gene TNFAIP3 (formerly called A20), functions as a tumor suppressor in NPC and mediates miR-125b-promoted NPC tumorigenesis by activating the nuclear factor κB (NF-κB) signaling pathway." (PMID 31456943, 2019). "All three up-regulated genes (CHD2, TET2, TNFAIP3) were annotated as tumor suppressors." (PMID 30425966, 2018). "Among a total of 48 tumor samples, 54% (n=26) demonstrated alterations in TNFAIP3." (PMID 28152507, 2017). "In our work, we found that NF-κB induced the expression of CXCL1, ICAM1 and TNFAIP3 after doxorubicin treatment only in a subset of tumors, suggesting that differences in responses may exist among tumor subtypes." (PMID 24344116, 2014). "TNFAIP3 is also frequently inactivated in subsets of B-lineage lymphomas that are characterized by NF-kB hyper activation and was therefore suggested to be a novel tumour suppressor." (PMID 24069342, 2013). "On the other hand, the abnormal expression of TNFAIP3 may promote the development of tumor." (PMID 38573314, 2024). "Our findings suggest a role of TNFAIP3 as a critical regulator of BRCA progression and tumor immunity." (PMID 41461391, 2026). "This study suggests a role of TNFAIP3 as a multi‐faceted regulator of BRCA progression and tumor immunity." (PMID 41461391, 2026). "Conversely, the overexpression of TNFAIP3 promotes EMT in vitro and facilitates tumour metastasis in vivo." (PMID 39724264, 2025). "This signature, comprising CCL19, ICOSLG, IL11, PTGES, TNFAIP3, and TRAF3IP3, has been demonstrated to predict survival outcomes across a range of cancers and to correlate with tumor progression at the level of multi‐omics." (PMID 40714831, 2025). "Genetic amplification of NF-κB signaling—through constitutive IKKβ activation or deletion of ubiquitin-modifying enzyme A20 (TNFAIP3)—enhances tumor-specific IFN-γ production, augments cytotoxic function, and promotes tumor rejection in preclinical models." (PMID 40562870, 2025). "TLR2, TLR4, and inflammasome inducing MR, NLRP3 can lead to tumor progression via the production of inflammatory cytokines (IL6, IL16), increased cell proliferation, and resistance to apoptosis (TNFAIP3)." (PMID 37599366, 2023). "Taken together, this information indicates that the upregulation of TNFAIP3 induced by BGA002 could be involved in the inhibition of the inflammation and in the restoration of the Th1/M1 susceptibility in MYCN-related SCLC and NB, leading to anti-tumor immunity restoration." (PMID 36765949, 2023). "CGP of PCL tissues revealed the tumor to be wildtype for CD79B, MYD88, CARD11, and TNFAIP3, with genomic alterations detected in SMO, CIITA, ETS1, HST1H1D, and SOCS1." (PMID 36342081, 2023).
tumor (continued). "We then performed qRT-PCR in SFE-treated ESCC cells and ground tumor lumps from the previous xenograft tumor assay, verifying that the expression of CXCL10, TNFAIP3, INHBA, and PLAU was indeed controlled by SFE in ESCC." (PMID 33374641, 2020). "In contrast, in both AP20187-treated DCIS-iFGFR1 and TNFAIP3 xenograft tumors, p-ERK1/2 immunostaining signals were detected in almost all of the tumor cells at stronger levels." (PMID 30111373, 2018). "In both vehicle-treated DCIS-iFGFR1 and TNFAIP3 KO xenograft tumors, p-ERK1/2 signals were only detected in a subset of tumor cells and these immunostaining signals were relatively weak." (PMID 30111373, 2018). "TNFAIP3 expression is required for FGFR1 signaling-promoted DCIS.COM cell proliferation, mammosphere growth, tumor growth and progression." (PMID 30111373, 2018). "Activation of iFGFR1 upregulated TNFAIP3 in an ERK2-dependent manner and TNFAIP3 is required for iFGFR1 activation-promoted DCIS.COM cell proliferation, mammosphere growth, tumor growth and progression." (PMID 30111373, 2018). "Candidate tumor suppressor genes identified in this region are B lymphocyte-induced maturation protein 1 (BLIMP1) and tumor necrosis factor α-induced protein 3 (TNFAIP3 or A20)." (PMID 24895570, 2014). "In contrast, miRNAs downregulated in rKGAS cells were found to regulate tumor suppressor genes such as IGF1R, TNFAIP3, and MTOR, suggesting that the acquisition of chemoresistance may involve altered regulation of both oncogenic and tumor-suppressive pathways." (PMID 40952575, 2025). "In contrast, CD8 effector cells exhibited downregulation of multiple key genes involved in tumor-suppressive transcriptional regulation (HIST1H1C, ZNF331, KLF6, and BTG1) and immune activation and trafficking (CXCR4, CD69, and TNFAIP3) in LS carriers, which was more severe in LS-CRC." (PMID 40909768, 2025). "We investigated the clinical significance of TNFAIP3 in a cohort of ESCC patients, collecting tissue samples from tumours and adjacent regions from 60 patients, who had comprehensive clinicopathological and follow‐up data from Zhongshan Hospital, Fudan University." (PMID 39724264, 2025). "The combination of anti‐tumour strategies targeting RARs/RXRs with TNFAIP3 presents a novel avenue for managing ESCC, wherein ZSH‐2208 plays a pivotal role due to its inherent anti‐tumour activity and its potential to facilitate the development of innovative RA analogues in the anti‐tumour domain." (PMID 39724264, 2025). "Subsequently, we conducted clustering and LASSO analysis on each tumor and found that the inhibitory and the stimulating immune checkpoints positively correlate with ZBP1, NLRP3, CASP1, CASP8, and TNFAIP3." (PMID 38002938, 2023). "Moreover, iv injection of TNF-α into the tail vein slightly upregulated NF-κB target genes (compared with the published articles), NFKBIA, and TNFAIP3, which were observed to examine the effect of TNF-α on the tumor NF-κB activity." (PMID 36110523, 2022). "Furthermore, FRGs, IRGs, DEGs, and genes in the blue module were intersected, and seven hub genes (JUN, TNFAIP3, NOX4, HMOX1, SOCS1, CYBB, and TFRC), related to both ferroptosis and tumor immunity, were obtained." (PMID 35174170, 2021). "In addition to using CA19-9 and D-dimer as preoperative prognostic markers, TNFAIP3/A20, TNM stage, and tumor differentiation grade should also be considered comprehensively after the surgery." (PMID 33578593, 2021). "A LOF mutation in the gene TNFAIP3, encoding for A20, is implemented as GOF in IKKc, since A20 is a tumor suppressor connected by a negative edge to IKKc." (PMID 34829885, 2021). "In our study, we found that tumor-derived ITGBL1-enriched EVs are directly transferred to lung and liver metastatic niche, and converts fibroblasts and stellate cells to CAFs by binding to TNFAIP3, and activating the NF-κB signaling pathway." (PMID 32139701, 2020).
tumor (continued). "Importantly, TNFAIP3 knockout not only inhibited the AP20187-induced proliferation and tumor growth of DCIS-iFGFR1 cells, but also further reduced baseline proliferation and tumor growth of DCIS-iFGFR1 cells without AP20187 treatment." (PMID 30111373, 2018). "The proteomic expression of TNFAIP3 in tumor stages, as analyzed by CPTAC proteomic data, shows a gradual decrease in TNFAIP3 protein expression as tumor staging progresses, and a significant negative correlation between TNFAIP3 protein levels and tumor stage (Spearman's ρ = −0.63, p < 0.001)." (PMID 41461391, 2026). "Therefore, we propose that TNFAIP3, a critical modulator of ZSH‐2208, may serve as a significant prognostic indicator for patients with ESCC and could also represent a potential target for anti‐tumour therapies." (PMID 39724264, 2025). "Tnfaip3 and CISH are important for host defense against infectious diseases and involved in negative feedback regulation of the tumor promoting effects." (PMID 25993608, 2015). "The other four genes (TNFAIP3/A20, COX2, CXCL12, and IER3L) were not expressed at significant levels (> 2 × background signal in at least 50% of all tumor samples)." (PMID 18248671, 2008).